BMPR2 (bone morphogenetic protein receptor type 2)
Diseases named in the same sentence as BMPR2 in open-access papers (continued):
Sharing a sentence is not in itself a finding about the gene and the disease.
familial pulmonary arterial hypertension (25 papers, 2012 to 2025). "Mutations in the bone morphogenetic protein receptor type-2 (BMPR2) are the most common genetic cause of familial pulmonary arterial hypertension." (PMID 39407331, 2024). "While mutations in the BMPR-2 have been linked to familial pulmonary arterial hypertension, multiple studies indicate decreased BMPR expression irrespective of mutations in the gene contributing to the pathogenesis of PH." (PMID 38891019, 2024). "BMPR2 mutation is the most common cause of heritable pulmonary arterial hypertension (HPAH), but rare in hereditary hemorrhagic telangiectasia (HHT)." (PMID 32756122, 2020). "A two-hit model is also proposed in hereditary pulmonary arterial hypertension (hPAH), in which Bmpr2 mutations is a strong susceptibility factor but where only 20% of carriers develop the disease." (PMID 31766155, 2019). "Mutations in the bone morphogenetic protein receptor 2 (BMPR2) gene can lead to hereditary pulmonary arterial hypertension (HPAH) and are detected in more than 80% of cases with familial aggregation of the disease." (PMID 24621962, 2014). "Although mutations in the BMPR2 gene account for a considerable portion of patients with familial pulmonary artery hypertension (FPAH), only 20–30% of carriers with mutations in this gene suffer from PH, indicating that other factors contribute to the onset of the disease." (PMID 34917122, 2021). "Inactivation or decreased expression of BMPR2 has a well-characterized association with familial pulmonary arterial hypertension, an effect which may be due to the role of BMPR2 in suppressing the response to TNF-mediated GM-CSF release." (PMID 31780722, 2019). "Hereditary hemorrhagic telangiectasia types 1 and 2 (HHT1, HHT2) and familial pulmonary arterial hypertension (FPAH) have been associated with mutations in ENG, ACVRL and BMPR2, respectively." (PMID 33195419, 2020). "Indeed, we observed dysregulation of KRIT1, related to cerebral cavernous malformations (CCM), APLN, related to lymphatic malformations, GNA11 related to capillary malformations and BMPR2, related to arteriovenous malformations and hereditary pulmonary arterial hypertension (HHT)." (PMID 38771392, 2024).
breast cancer (24 papers, 2010 to 2025). A primary or metastatic malignant neoplasm involving the breast. "In support of this, the expression of a dominant-negative BMPR2 potentiated tumour cell proliferation and lung metastases in a mouse model of mammary carcinoma formation, suggesting that BMPRII loss or silencing is probably cell line- or tissue type-specific." (PMID 32708289, 2020). "Since BMPR2 has a well-demonstrated association with reducing inflammation both physiologically and in models of breast cancer, we examined the specific associations between BMPR2 expression and the xCELL-determined abundance of cell types." (PMID 31780722, 2019). "Given that loss of stromal BMPR2 expression increases cytokine production in a mouse model of breast cancer, further studies are warranted to investigate whether mesenchymal BMP signaling, modulated by GREM1 and ISLR, could also be involved in shaping the immunosuppressive tumor microenvironment." (PMID 33197448, 2021). "We report 3 women with BMPR2-related PAH who developed early onset epithelial cancers: 2 breast cancers (34 and 54 years of age) and 1 colorectal cancer (47 years of age)." (PMID 40923964, 2025). "In breast cancer, BMPR2 also exerts a suppressive function, primarily via its action in the tumor stroma." (PMID 40923964, 2025). "In this regard, BMPR2 overexpression has also been reported in the peripheral blood of patients with advanced breast cancer, possibly reflecting altered systemic signaling or a compensatory mechanism with potential diagnostic value." (PMID 40923964, 2025). "When Bmpr2 is dominantly expressed as a negative regulator in a mouse model of breast cancer, it promotes tumor metastasis by creating a paracrine inflammatory microenvironment." (PMID 37740953, 2023). "BMPR2 has a tumor suppressor function in the mammary epithelium and microenvironment, and its disruption accelerates breast cancer metastasis." (PMID 34903128, 2021). "Disruption of BMPR2 has also been found to promote metastasis of mammary tumours, suggesting that BMPR2 has tumour-suppressive function in mammary epithelial cells." (PMID 32714600, 2020). "Genetic alterations in BMPR1A, BMPR1B, or BMPR2 were found in around 6, 7, or 5% of patients with breast cancer, respectively, with the major form of genetic alternation being an upregulation of mRNA encoding BMP receptors (data not shown)." (PMID 31409851, 2019). "When queried for the three most common BMP receptors: BMPR1a, BMPR2 and BMPR1b, BMPR1a and BMPR2 are largely equally distributed for high and low expression between the four largest molecular subtypes of breast cancer." (PMID 26274893, 2015). "When BMPR2 is expressed as a dominant negative in a mouse model of breast cancer, it enhances tumor metastasis through a paracrine inflammatory microenvironment." (PMID 26274893, 2015). "We have previously reported that all six BMP specific receptors (ACVR1, BMPR1A, BMPR1B, ACVR2A, ACVR2B, and BMPR2) are uniformly expressed among the breast cancer cell lines studied here." (PMID 22118688, 2011). "For example, dominant-negative BMPR2 affects the growth of human breast cancer cells in vitro by blocking cells in G1 of the cell cycle." (PMID 20187934, 2010). "Inhibiting ZEB1-mediated immune suppression, either directly or by inhibiting ZEB1-regulated immune modulators like BMPR2, may be a therapeutic approach to promote antitumor immune activity in breast cancer." (PMID 31780722, 2019). "Inhibition of BMPR2 has been shown to inhibit growth and viability of breast cancer cells." (PMID 26437339, 2015). "Other miRNAs recently implicated in breast cancer include miR-100, shown to target SMARCA5, SMARCD1, and BMPR2 genes, which directly influence tumor cell proliferation, and miR-30c, known to target TWF1 and IL-11, both of which are expressed in the MaSC/basal lineage." (PMID 26080807, 2015).
breast cancer (continued). "In summary, a shift in the expression pattern of BMPs in breast cancer, including increased BMP8A, BMPR1B and decreased BMP6, BMP7, ACVR1C, TGFBR2, TGFBR3 and BMPR2 presented a subtype specific role." (PMID 37333824, 2023). "BMP2, BMP4, GDF11 and TGFBR2 had relatively higher levels in bone metastases of breast cancer while BMP5, BMP7, BMPR2, BMPR1A and ACVR2A presented lower expression in the bone metastases, in the E-MTAB-4003 dataset." (PMID 37333824, 2023). "SMAD3 BMPR2, XIAP, and ESR1 have also been proven to be regulated by OS in skin fibroblasts, vascular smooth-muscle cells, PC6.3 cells, and breast cancer." (PMID 35954205, 2022). "Here, we assessed the expressions of six circRNAs that have been reported to be abnormally expressed in breast cancer: circ_0108942, circ_0001785, circ-ERBB2, circ-BMPR2, circ-UBE2D2, circ-IRAK3." (PMID 34732216, 2021). "In contrast, in breast cancer BMPR1A activity was shown to promote cell proliferation via SMADs, whereas results for BMPR2 are contradictory." (PMID 22277058, 2012).
endothelial dysfunction (24 papers, 2011 to 2025). In vascular diseases, endothelial dysfunction is a systemic pathological state of the endothelium (the inner lining of blood vessels) and can be broadly defined as an imbalance between vasodilating and vasoconstricting substances produced by (or acting on) the endothelium. "Loss of BMPR2 signaling disrupts vascular homeostasis by inducing endothelial dysfunction and vascular smooth muscle proliferation, leading to increased vascular resistance and contributing to the development of PAH." (PMID 40720495, 2025). "The downregulation of miR-191 activates bone morphogenetic protein receptor 2 (BMPR2) mutations by preventing BMPR2 degradation, which inhibits exaggerated inflammatory responses, rescues age-related endothelial dysfunction, and reverses PAH." (PMID 35656114, 2022). "BMPR2 deficiency in HPAECs led to endothelial dysfunction seen in PAH characterized by hyperproliferation and cytokine release; these processes were dependent on the nmMLCK pathway, as specific inhibition negated these adverse effects." (PMID 36362426, 2022). "Genetic bone morphogenic protein receptor 2 (BMPR2) deficiency is associated with familial PAH, and the biology of BMPR2 signaling has provided insight as to molecular mechanisms driving endothelial dysfunction in the development of PAH." (PMID 32392789, 2020). "Using RNA sequencing analysis, Rhodes and colleagues found a novel pathway involving downregulation of endothelial COL4 and EFNA1 that underlies BMPR2-related endothelial dysfunction in PAECs." (PMID 26373550, 2015). "Approximately 20% of patients with IPAH carried mutations in bone morphogenetic protein receptor type 2 (BMPR2), where a loss of BMPR2 function may compromise the integrity of the endothelial barrier and contribute to endothelial dysfunction by mediating endothelium-derived nitric oxide bioactivity." (PMID 33282881, 2020). "Beyond their classical metabolic roles, these molecules act as potent modulators of vascular remodeling, endothelial dysfunction, inflammation, and oxidative stress, intersecting with key pathways such as BMPR2 and TGF-β signaling." (PMID 41169887, 2025). "We found that Orai1 knockdown in PAH-hPECs induces increased BMPR2 expression, suggesting that Orai1 inhibition should partly reduce endothelial dysfunction that occurs in PAH by restoring BMPR2 expression." (PMID 41212057, 2025). "We found PTPN1 as a novel modifier of BMPR2 signaling and showed that PTPN1 is decreased in the blood of PAH patients and PTPN1 deficiency is associated with induction of markers of endothelial dysfunction." (PMID 36672250, 2023). "We identified PTPN1 as a novel regulator of BMPR2 signaling in PAECs, which is downregulated in the blood of PAH patients, and documented that downregulation of PTPN1 is linked to endothelial dysfunction in PAECs." (PMID 36672250, 2023). "Taken together, BMPR2 silencing in HPAECs leads to endothelial dysfunction as measured by increased cellular proliferation, viability, and cytokine release, which are all attenuated by inhibition of the nmMLCK pathway." (PMID 36362426, 2022). "Since BMPR2 silencing demonstrated upregulation of cytoskeletal proteins, we next sought to evaluate for the endothelial dysfunction that is characteristic of vascular remodeling." (PMID 36362426, 2022). "Similarly, haplo-insufficient BMPR2 mutant rats developed severe dysfunction of the cardio-pulmonary-vascular system, such as distal vessel muscularization, loss of microvascular vessels, inflammation, RV and endothelial dysfunction as well as intrinsic cardiomyocyte dysfunction." (PMID 33374819, 2020). "Intriguingly, pulmonary BMPR2 expression is over expressed in vascular endothelium, implying that BMPRS plays a key role in endothelial dysfunction underlying the development of PAH." (PMID 26373550, 2015).
endothelial dysfunction (continued). "Furthermore, we demonstrated that targeting endothelial dysfunction by activation of BMPR2 with WT BMP9 was ineffective in reversing or preventing the development of PAH in rat models." (PMID 40720495, 2025). "FK506 (tacrolimus) interacts with FKBP12, activates Smad1/5/8 with or without BMPR2 mutations, recovers endothelial dysfunction, and ameliorates PH53–55." (PMID 38182755, 2024). "A previous study demonstrated that the BMPR2 variant can lead to endothelial dysfunction and PAH in the absence of protective modifiers." (PMID 38473983, 2024). "Despite previous studies’ findings on EC- Cav-1/BMPR2 depletion as an important switch towards endothelial dysfunction, more specific information about what triggers the process remains unclear." (PMID 37908354, 2023). "Since endothelial dysfunction in the pulmonary circulation is the initial trigger for PAH, this may explain why the haploinsufficiency of BMPR2 is most likely to cause PAH despite the receptor being expressed in many tissues." (PMID 35504921, 2022). "We provide evidence that loss of BMPR2 alters biophysical properties of ECs and the matrisome, which integrates TGFβ-SMAD and integrin signaling into an accelerating feed-forward loop for activating TGFβ responses in endothelial dysfunction." (PMID 31826007, 2019). "Despite the increased survival and the hemodynamic, anatomical and histological improvement, most of the conventional markers of PAH such as membrane depolarization, endothelial dysfunction and downregulation of BMPR2 and KV1.5, were unaffected or modestly affected by quercetin." (PMID 25460361, 2014). "Overall, these results confirm that in addition to BMPR2 silencing, HPAECs treated with VEGF, another known PAH-inducing cellular mechanism, leads to endothelial dysfunction and hyper-migration mediated by the nmMLCK pathway." (PMID 36362426, 2022). "PAH is associated with mutations in the bone morphogenetic protein receptor type II (BMPR2) gene, impaired BMPRII signaling, pulmonary vascular remodeling and endothelial dysfunction." (PMID 34831453, 2021). "In vitro, FK506 activated downstream BMPR2 signaling via SMAD1/5, MAPK and ID1 signaling in healthy PA endothelial cells (PAECS), while normalizing endothelial dysfunction in PAH PAECs." (PMID 33374819, 2020). "As endothelial dysfunction plays an important role in PH pathogenesis and as the BMPR2 receptor is highly expressed in endothelial cells, we aimed to investigate the role of PTPN1 in modulating BMPR2 signaling and its effect on PAEC function in PAH." (PMID 36672250, 2023).
idiopathic pulmonary arterial hypertension (21 papers, 2011 to 2024). A sporadic form of pulmonary arterial hypertension (PAH) characterized by elevated pulmonary arterial resistance leading to right heart failure. "In 2000, the International Primary Pulmonary Hypertension (PPH) Consortium demonstrated that familial PAH (FPAH) is caused by mutations in BMPR2, located on chromosome 2, encoding a TGF-β type II receptor." (PMID 33256119, 2020). "This genetic association study assesses novel susceptibility genes other than BMPR2 in patients with idiopathic pulmonary arterial hypertension." (PMID 32236489, 2020). "Reduction of RAD51 is observed not only in pulmonary microvascular endothelial cells but also in pulmonary artery smooth muscle cells isolated from rats with heterozygous BMPR2 mutation and from human idiopathic pulmonary arterial hypertension patients." (PMID 30272025, 2018). "Mutations in the bone morphogenetic protein receptor 2 (BMPR2) gene can lead to idiopathic pulmonary arterial hypertension (IPAH)." (PMID 21801371, 2011). "Moreover, mutations in BMPR2 are associated with familial and sporadic primary pulmonary hypertension (PPH) in humans, and it is notable that many PPH-causing mutations result in truncation of the tail domain." (PMID 23967299, 2013). "Most BMPR2 variants were reported previously in patients with idiopathic pulmonary arterial hypertension (IPAH), while recent NGS and functional studies have revealed that p.S987F in BMPR2 caused isolated POI by perturbing BMP15/BMPR2/SMAD signaling and GCs proliferation." (PMID 36793102, 2023). "BMPR2 mutations were found to be present in 55%−70% of high pulmonary arterial hypertension (HPH) cases and 11%−40% of idiopathic pulmonary arterial hypertension (IPH) cases." (PMID 34793329, 2021). "Although some cases of human idiopathic pulmonary arterial hypertension (IPAH) are due to autosomal dominant mutations in the BMPR2 gene, most patients with IPAH do not have this mutation." (PMID 23700405, 2013). "Idiopathic pulmonary arterial hypertension (IPAH) is a fatal disease with high heritability; however, the bone morphogenetic protein receptor 2 (BMPR2) gene only accounts for 17% of IPAH." (PMID 32236489, 2020).
Obesity (11 papers, 2011 to 2025). Accumulation of substantial excess body fat. "As essential for BMP signaling BMP receptor 2 (BMPR2) was implicated in adipogenesis and pathophysiology of obesity." (PMID 31831718, 2019). "In a subgroup of 161 subjects the rs6717924 obesity risk allele was associated with visceral BMPR2 mRNA expression and BMI." (PMID 21311592, 2011). "Carriers of the rs6717924 A-allele (i.e. obesity risk allele) had higher BMPR2 mRNA expression in visceral adipose tissue compared to carriers of the non-risk alleles (P = 0.042 adjusted for age, sex and BMI; N = 161)." (PMID 21311592, 2011). "Association analyses of the BMPR2 genetic variants with obesity in the Leipzig and the Sorbs cohorts." (PMID 21311592, 2011). "Undoubtedly, studies targeting functional consequences of BMPR2 obesity risk variants on BMPR2 transcription are inevitable to clarify whether genetic variants can explain variation in BMPR2 mRNA expression." (PMID 21311592, 2011). "To determine whether genetic variants in the BMPR2 are related to adipose tissue BMPR2 mRNA expression and to the obese human phenotype, we sequenced the BMPR2 and evaluated the association between representative variants and obesity related traits in two independent Caucasian cohorts from Germany." (PMID 21311592, 2011). "Our findings suggest that miR-6402 is a novel anti-adipogenic miRNA that combats obesity by inhibiting the BMP4/BMPR2 signalling pathway and subsequently reducing adipose tissue expansion." (PMID 40028748, 2025). "As one of the 18 overlapping DEGs in obesity and COPD, PRKCB (encoded PKCβprotein) had the PPI with BMPR2." (PMID 37886639, 2023). "However, the heterogeneity of the samples due to cardiopulmonary condition (e.g., chronic lung diseases, inflammation), obesity, sex, and type-2 bone morphogenetic protein receptor (BMPR2) mutations may impact blood vessel formation, SMC DNA synthesis and migration and the signaling pathways." (PMID 32371931, 2020). "They complement regulation associated with lipoproteins and lipid metabolism and adipogenesis, encompassing CFHR1, CFHR3, and BMPR2 protein–protein interactions, given marked obesity is a common finding in PWS." (PMID 32384786, 2020). "We therefore performed a systematic study on the potential role of BMPR2 in the pathophysiology of obesity by combining data from genetic, evolutionary, phenotypic and adipose tissue expression studies." (PMID 21311592, 2011). "Since BMPR2 is considered a plausible obesity candidate gene, we investigated its role in the pathophysiology of human obesity." (PMID 21311592, 2011). "Combined BMPR2 genotype-phenotype-mRNA expression data as well as evolutionary aspects suggest a role of BMPR2 in the pathophysiology of obesity." (PMID 21311592, 2011). "BMPR2 mRNA expression correlated with measures of obesity and fat distribution, as well as with traits of glucose metabolism and insulin sensitivity." (PMID 21311592, 2011). "As for patients with COPD, the Activin A Receptor Type 2B (ACVR2B) and Transforming Growth Factor Beta 1 (TGFβ1), which were the key modulators of BMPR2 pathway, were significantly downregulated, as well as the obesity-related gene Apelin Receptor Early Endogenous Ligand (APELA)." (PMID 37886639, 2023). "Moreover, paradoxically, increased BMPR2 expression has been reported in the adipose tissue and has been suggested to play a role in the pathophysiology of obesity." (PMID 30689673, 2019). "Since BMPR2 is also a plausible obesity candidate gene, we searched for evidence supporting the “thrifty gene” hypothesis by investigating its potential role in the pathophysiology of human obesity." (PMID 21311592, 2011). "Correlations of BMPR2 expression with obesity and relevant metabolic traits suggest that BMPR2 mRNA expression in human adipose tissue might be related to progression of obesity but it remains unclear whether it is due to the extended fat mass or vice versa." (PMID 21311592, 2011).